LYZ (lysozyme)
Diseases named in the same sentence as LYZ in open-access papers (continued):
Sharing a sentence is not in itself a finding about the gene and the disease.
cancer (69 papers, 2011 to 2026). A tumor composed of atypical neoplastic, often pleomorphic cells that invade other tissues. "Specifically, genes like ADD3 and LYZ have been previously implicated in potential roles related to the progression and metastasis of certain cancers." (PMID 38240686, 2024). "Glycolysis in Lgr5 expressing cancer cells was reduced along with the loss of LYZ+ cells by Dkk2 knockout." (PMID 38659853, 2024). "To analyze the consequence of the loss of LYZ+ cells by Dkk2 knockout in cancer stem cell niche formation, we enriched Lgr5 positive cells that consist of stem cells, stem cell niche cells and transit amplifying cells in the homeostatic condition." (PMID 38659853, 2024). "Among these factors, only antifungal drug use was found to be related to the lysozyme level in cancer patients; it was also significantly associated with the SIgA level (P < 0.01)." (PMID 27294141, 2016). "The western blotting analyses showed the presence of high levels of LYZ in the cancer cells; in particular, an LYZ form at a high molecular weight (about 50 kDa) was observed, corresponding to the trimeric form of the protein." (PMID 40046560, 2025). "A wider function for LYZ in carcinogenesis is suggested by the pan-cancer study showing differential expression of LYZ in several other cancer types, which calls for more research into its processes in diverse malignancies." (PMID 41514850, 2025). "The LYZ gene also showed differential expression in a number of other cancer types, according to a pan-cancer study, indicating that it contributes to the development and spread of malignancies." (PMID 41514850, 2025). "Confocal microscopy analysis confirmed that HNF4α1 knockdown rescued the presence of LYZ+ cancer cells in KO organoids." (PMID 38659853, 2024). "HNF4A binding on the Sox9 promoter inhibited the formation of LYZ+ cancer cells exhibiting Paneth cell characteristics." (PMID 38659853, 2024). "In the liver metastatic foci, DKK2 knockout rescued HNF4A protein levels followed by reduction of lysozyme positive cancer cells." (PMID 38659853, 2024). "Employing lysozyme expression and Paneth cell module scores (Pangalo database) as criteria, we have identified LYZ+ cancer cells harboring Paneth cell properties across 5 clusters." (PMID 38659853, 2024). "In vitro co-culture with lysozyme has led to inhibition of proliferation in a variety of cancer cell lines." (PMID 38505585, 2024). "The percentile of LYZ+ cells in total cancer cells was decreased about 3-fold in Dkk2 knockout metastasized cells (KO) compared to the AKP control cells in liver." (PMID 38659853, 2024). "In this regard, the delivery of cytotoxic proteins, such as granzyme B (GrB) and lysozyme, has emerged as a promising approach in cancer treatment." (PMID 39166136, 2024). "This synergistic approach leverages the targeting capabilities of lysozyme to enhance the internalization of granzymes into cancer cells." (PMID 39166136, 2024). "In correlation with our murine scRNA-seq data IPA results, glycolysis emerged as the 2nd-ranked enriched pathway in LYZ+ cancer cells compared to LYZ− cancer cells." (PMID 38659853, 2024). "In order to quantify LYZ+ cancer cells in the mouse model of liver metastasis, tdTomato positive cells in the liver were identified as the implanted organoid-derived cancer cells then, LYZ+ cells were calculated." (PMID 38659853, 2024). "In correlation with our murine scRNA-seq data IPA results, glycolysis emerged as the second-ranked enriched pathway in LYZ+ cancer cells compared to LYZ- cancer cells." (PMID 39535280, 2024). "We have shown that DKK2 is required for the formation of LYZ+ cancer cells carrying Paneth cell properties." (PMID 38659853, 2024). "The percentile of LYZ+ cells in total cancer cells was decreased about threefold in Dkk2 knockout metastasized cells (KO) compared to the AKP control cells in liver." (PMID 39535280, 2024).
cancer (continued). "scRNA-seq analyses for mouse and human metastatic colon cancers have identified the existence of LYZ+ cancer cells harboring Paneth cell properties, in particular, glycolysis for stem cells." (PMID 39535280, 2024). "For example, lysozyme (Lyz) is considered a cancer marker, and its detection is essential for the early diagnosis of cancers." (PMID 36770595, 2023). "CAP treatment, by oxidizing and nitrating the amino acids of lysozyme, provides a useful method to achieve this goal and design new cancer drugs." (PMID 37759771, 2023). "The mRNAs most associated with TUCP_002240 are LYZ and TSPAN1; LYZ is a component of innate immunity, and TSPAN1 has a regulatory role in cancer." (PMID 36838374, 2023). "The content of lysozyme in saliva can also reflect the process of malignant tumors to a certain extent." (PMID 34925025, 2021). "The biocompatibility of CuS-BSA and CuS-BSA/Lysozyme was elicited in vitro on HeLa and U-87 MG cancer cell lines, and immortalized human hepatocyte (IHH) cell line." (PMID 34578471, 2021). "We also explored the role of lysozyme as a cancer prognostic marker to predict patient’s outcomes and cancer recurrence probability." (PMID 34925025, 2021). "Although these results suggest that the lysozyme with modified structure and activity application has potential use in cancer treatment, these are pilot studies, and the effects in in vivo conditions must be further analysed." (PMID 34830132, 2021). "Considering the stem cell-maintaining role of the Paneth cells in the small intestine, it is probable that the ectopic differentiation of lysozyme-positive cells induced by Apc-KO significantly contributes to cancer development." (PMID 33597597, 2021). "It has been also shown that lysozyme has anti-cancer activity and can directly activate immune cells or increase tumour-cell immunogenicity." (PMID 34830132, 2021). "More recently, studies have revealed the anti-cancer activities of lysozyme in multiple types of tumors, potentially through its immune-modulatory activities." (PMID 34925025, 2021). "Lysozyme can not only be regarded as a drug candidate for cancer treatment but also be considered as a promising biomarker for the early diagnosis, staging and prognosis of tumors." (PMID 34925025, 2021). "With further researches, lysozyme as a biomarker to monitor the occurrence and development of diseases is not only in the field of cancers." (PMID 34925025, 2021). "Based on its regulatory effects on the human immune system, lysozyme has the potential to be a prognostic marker in the initiation, development, as well as metastasis of most cancers." (PMID 34925025, 2021). "In 1978, lysozyme successfully authorized a patent in Japan for the treatment of cancer, and it was proposed that lysozyme oral agent can strengthen the immunity of cancer patients." (PMID 34925025, 2021). "Various egg components, including lysozyme, avidin, IgY, lecithin, and bioactive peptides, display anti-cancer, antihypertensive, anti-inflammatory, and antimicrobial activities, and have great industrial opportunities in the pharmaceutical sector." (PMID 34976961, 2021). "As an anti-cancer agent, human lysozyme goat milk for the prevention of graft versus host disease in patients with blood cancer undergoing a donor stem cell transplant." (PMID 34925025, 2021). "We also evaluated the role of lysozyme as a promising cancer marker for prognosis to indicate the outcomes recurrence for patients." (PMID 34925025, 2021). "In this study, we found that the levels of salivary SIgA and lysozyme in cancer patients were significantly different from those in healthy control individuals." (PMID 27294141, 2016). "The content of lysozyme was much more in the hematopoietic system tumor group (56.13 ± 7.61 ng/mL) than that in the digestive tract malignant tumor group (52.39 ± 12.64 ng/mL) (P < 0.05)." (PMID 27294141, 2016).
cancer (continued). "The antibacterial properties of egg white can be attributed to the presence of lysozyme, which is used as an anti-cancer drug and for the treatment of human immunodeficiency virus (HIV) infection." (PMID 25706123, 2015). "This review focuses on mammalian C-type LYZ (referred to as LYZ hereafter unless specified) and integrates multi-omics data (transcriptomics and proteomics) with clinical and mechanistic research to systematically dissect its dual roles in cancer." (PMID 41622693, 2026). "LYZ is a promising potential biomarker and therapeutic target in some cancers." (PMID 41622693, 2026). "Therefore, the results presented here open the way to a potential selective treatment with the RPL system of cancer cells on the basis of a high ectopic expression of LYZ and the presence of P in cancer cells." (PMID 40046560, 2025). "From these clusters, five major cell types were identified via classical cell markers, including T cells (CD3E, CD8A, CD3D), B cells (CD19, MS4A1, CD79A), myeloid cells (CD14, CD68, LYZ), endothelial cells (PECAM1, VWF, CDH5) and cancer-associated fibroblasts (CAFs) (ACTA2, FAP, PDGFRB)." (PMID 39941131, 2025). "Furthermore, to extend this treatment to other cancer types, the variability in P levels and in LYZ expression among different cell types should be investigated with specific focus on ectopic LYZ expression on the cell surface." (PMID 40046560, 2025). "LYZ+ cancer cell population is distinct in metastasis samples." (PMID 38659853, 2024). "LYZ+ cancer cells exhibit Paneth cell properties in both mouse and human systems." (PMID 38659853, 2024). "Notably, key players in glycolysis such as ALDOB and KDELR3 genes are increased in LYZ+ cancer cells." (PMID 38659853, 2024). "LYZ expression over 2.0 (third quantile, round 1) and Paneth module scores over 0.2 (third quantile, round 2 to avoid getting 0) single cells were identified as LYZ+ cancer cells harboring Paneth cell properties, 1%, 13%, and 24% in normal, primary tumor, and metastasis samples, respectively." (PMID 39535280, 2024). "LYZ is associated with neutrophil degranulation and host defense peptides, whereas COL1A1, COL1A2 along with HGF, TNC, and VEGFA are all part of the PI3K pathway, which plays an important role in cancer progression, and has been implicated in TNT regulation." (PMID 37955637, 2023). "Briefly, myeloid cells (LYZ+), lymphocytes (CD3D+), osteoclasts (ACP5+), endothelial cells (CLDN5+), perivascular-like cells (PVL) (RGS5+TAGLNhigh), cancer-associated fibroblasts (CAFs) (TAGLNlowACTA2+) and proliferative cells (MKI67+) were identified in the study." (PMID 36596773, 2023). "Therefore, enhancing the efficiency of lysozyme as a cancer therapy drug through structural and functional modifications can be essential in this field." (PMID 37759771, 2023). "In as early as 1964, lysozyme was reported to be used to treat cancer." (PMID 34925025, 2021). "In the ceRNA co‐expression network, LYZ was found to be differently expressed in several cancers." (PMID 33047898, 2020). "Furthermore, the salivary SIgA was significantly different among different cancer groups, while salivary lysozyme showed significant difference only between patients suffering from digestive tract malignant tumor and hematopoietic system tumor." (PMID 27294141, 2016). "Therefore, it is of interest to detect if both the salivary SIgA and lysozyme can act as the biomarkers to monitor several cancers in clinical use." (PMID 27294141, 2016). "However, the lysozyme content was higher in cancer patients than that in normal controls (P < 0.01)." (PMID 27294141, 2016). "Specifically, neutrophils contain multiple enzymes such as, myeloperoxidase, interleukin-6 (IL-6), defensins, lysozyme and collagenase which may directly promote cancer cell intravasation and extravasation." (PMID 26544968, 2015).
cancer (continued). "LYZ expression over 2.0 (3rd Quantile, round 1) and Paneth module scores over 0.2 (3rd Quantile, round 2 to avoid getting 0) single cells were identified as LYZ+ cancer cells harboring Paneth cell properties, 1%, 13% and 24% in normal, primary tumor and metastasis samples, respectively." (PMID 38659853, 2024). "Moreover, normal mice taking lysozyme were less likely to develop cancer." (PMID 34925025, 2021). "In addition, lysozyme possesses an anti-proliferative effect against cancer and lung fibroblasts." (PMID 32050422, 2020). "We preliminarily concluded that malignant tumor may influence the contents of SIgA and lysozyme." (PMID 27294141, 2016). "We selected SIgA and lysozyme as the objects of the study aiming to understand the oral mucosal immune status of cancer patients and make clear whether these antibacterial proteins in saliva were influenced by patients' health status and certain medical treatment therapy." (PMID 27294141, 2016). "Thus, the raised concentration of lysozyme in cancer patients may be explained by antitumor effect of lysozyme." (PMID 27294141, 2016). "The riboflavin–phosphocholine–light (RPL) system induces lysozyme (LYZ) photopolymerization in vitro, affecting the cell viability of cancer cells, in both 2-dimensional and 3-dimensional cell cultures." (PMID 40046560, 2025). "We also discovered some unidentified regulators such as TM9SF3, LYZ, and ARL4C, which are potentially engaged in the cellular transition from the cancer stem cells into metastatic malignant cells." (PMID 34732701, 2021). "In Elyada’s scRNA-seq analysis, ductal cancer cells in human PDAC were clustered in two major subtypes: the classic (by TFF1, TFF2, LYZ, VSIG2, and CEACAM6 marker genes) and secretory (by SPP1, CLU, CTGF, and COL18A1 marker genes) subtypes." (PMID 34035226, 2021). "On the basis of our molecular results for LYZ, we evaluated the possibility that the effects of RPL treatment could be related to differences in LYZ expression between cancer cells and MSCs." (PMID 40046560, 2025). "The neutrophil degranulation complex was defined by the terms antimicrobial peptides (R-HAS-6803157), neutrophil degranulation (R-HSA-6798695), response to yeast (GO:0001878), and transcriptional misregulation in cancer (KEGG:05202); it included the proteins ELANE, H3-5, MPO, LYZ, and PRTN3." (PMID 39997396, 2025). "The RPL treatment of nontumoral, mesenchymal stem cells, or cancer cells shows a distinct behavior, depending on the ectopic presence of LYZ." (PMID 40046560, 2025). "Moreover, for CTSE, CXCL17, and LYZ, we explored the correlation between their expression and CLDN18.2 expression in three cancers." (PMID 39555091, 2024). "YKL-40 gene expression was primarily increased in the fibroblast (gene annotation: COL1A, BGN, DCN), myeloid (gene annotation: CD68, LYZ, AIF1), cancer (gene annotation: EPCAM, KRT7, KRT18), and B-cell (gene annotation: CD79A, CD79B) populations in cancer tissue compared to healthy tissue." (PMID 35631632, 2022). "Although lysozyme can also be used as a prognostic marker protein of MBC, studies have found that the expression of lysozyme in MBC patients was related to the poor prognosis of cancer." (PMID 34925025, 2021). "It was found that lysozyme at a concentration of 100 μg/L could effectively inhibit the growth of cancer cells without showing any toxicity on normal cells." (PMID 34925025, 2021). "We find that the genes specifically expressed in the supratentorial tumors from these publications (such as HLA-DRA, LYZ, CD74, F13A1, and TRIM22) tend to be expressed in cells within the microglia-type cluster, whereas the infratentorial tumors have higher expression of cancer cell-related genes." (PMID 31427603, 2019).
infectious disease (15 papers, 2014 to 2026). A disorder directly resulting from the presence and activity of a microbial, viral, or parasitic agent in humans. "The close association of lysozyme with cells of the immune system may indicate that this enzyme contributes to defense against infectious diseases." (PMID 32858831, 2020). "Lysozyme increases the abundance of bacteria associated with a healthy gut and decreases those associated with disease, and lactoferrin stimulates intestinal cell development, promotes bifidobacteria and lactobacilli growth, and reduces risk of infectious disease." (PMID 33673498, 2021). "Recombinant human lactoferrin and lysozyme are used in nutraceutical preparations as antimicrobial agents with clinical efficacy in the treatment of infectious diseases in humans." (PMID 33810073, 2021). "This review is focused on the applications of lysozyme in medicine, (the treatment of infectious diseases, wound healing, and anti-biofilm), veterinary, feed, food preservation, and crop protection." (PMID 34943746, 2021). "In teleost fish, serum lysozyme is an indicator of immune response, protecting fish from infectious disease due to elevated levels decomposing the cell wall of Gram-positive and Gram-negative bacteria." (PMID 33521040, 2020). "The purpose of this study is to evaluate the significance of differences in serum angiotensin converting enzyme and lysozyme levels of patients with ocular involvement of other autoimmune inflammatory and infectious diseases." (PMID 26879979, 2016). "Perhaps, the challenging legacy of Alexander Fleming, together with the more recent bacterial resistance to commercial antibiotics, offer the explanation for the boost in research on the potential use of lysozyme for the treatment of infectious diseases." (PMID 25437608, 2014). "Immunostimulants stimulate natural killer cells, complement, lysozyme activity, and antibody responses in fish and shellfish primarily by promoting phagocytosis, thereby enhancing the killing of pathogens and resistance to infectious diseases." (PMID 39061919, 2024). "Lysozyme plays a crucial role in protecting against infectious diseases by breaking down glycosidic bonds present in the peptidoglycan of cell walls, regardless of whether they are gram-positive or gram-negative." (PMID 38473073, 2024). "When organisms meet bacterial infectious diseases or other stimulus factors, changes in lysozyme activity may enhance immune defenses." (PMID 27046191, 2016). "The potential use of lysozyme to treat infectious diseases is receiving much attention." (PMID 25437608, 2014). "The lysozyme activity can act as a non-specific molecule that beneficially protects the fish from the infectious disease through the breakdown of 1,4 glycosidic bonds present in the peptidoglycan of both Gram-positive and Gram-negative cell walls." (PMID 33467482, 2021).
neurodegenerative disease (4 papers, 2012 to 2022). A disorder of the central nervous system characterized by gradual and progressive loss of neural tissue and neurologic function. "The use of β-lactam antibiotic ceftriaxone as a potential drug to ameliorate neurodegenerative diseases was studied using GFAP and lysozyme showing that the presence of ceftriaxone could reduce significantly the rate of UV photodenaturation of the proteins." (PMID 30065161, 2018).
blood disorders (3 papers, 2019 to 2025). "Therapeutically, management centers on treating the underlying hematologic malignancy to reduce lysozyme production." (PMID 41181405, 2025). "The perivisceral lymph nodes appeared subverted from predominantly atypical epithelioid or sarcomatoid medium-sized cells that were CD68- and lysozyme-positive, as well as CD45RO, typical markers in the differential diagnosis with other haematological diseases." (PMID 34948520, 2021).
hereditary disease (3 papers, 2012 to 2021). A disease that is caused by genetic modifications where those modifications are inherited from a parent's genome. "Lysozyme amyloidosis is a hereditary disease, which is characterized by the deposition of lysozyme amyloid fibrils in various internal organs." (PMID 35111814, 2021).
cardiovascular diseases (2 papers, 2021 to 2022). "Therefore, lysozyme may be more effective than antibiotics in inhibiting cardiovascular diseases caused by Cnm-positive S. mutans." (PMID 35181690, 2022). "Thus, Gs-Re combined with a small amount of lysozyme may provide a novel therapeutic strategy for vascular remodeling-associated cardiovascular diseases." (PMID 35004822, 2021).